JAK2 (Janus kinase 2)
Diseases named in the same sentence as JAK2 in open-access papers (continued):
Sharing a sentence is not in itself a finding about the gene and the disease.
tumor (continued). "Accumulating evidence implicates the important role of JAK2/STAT3 in tumor and macrophage polarization." (PMID 28630636, 2017). "BM cells can also promote the expansion of myeloid-derived suppressor cells (MDSCs) within the tumor microenvironment by inducing secretion of VEGF from MCs that in turn can activate JAK2/STAT3 signaling in myeloid progenitor cells." (PMID 28626727, 2017). "Taking together, the data suggested that QRHX inhibited tumor cell-TAMs interactions possibly through blocking CXCL12/CXCR4/JAK2/STAT3 signaling pathways and then regulated macrophages polarization." (PMID 28630636, 2017). "In H460 lung cancer cells, curcumin was able to reduce the tumor spheres and repress tumor growth in xenograft mouse model via inhibiting the JAK2/STAT3 signaling pathway." (PMID 28156178, 2017). "In the present study, we found that IL-6 neutralizating antibody partly suppressed the STAT3 or JAK2 phosphorylation, which suggested that IL-6 contributed partially to the tumor-promoting effect of CAFs on GC cells." (PMID 28186964, 2017). "The anti-tumor action of the FXR ligand was associated with the inhibition of several leptin-induced pathways, such as JAK2/STAT3, AKT and MAPK." (PMID 26899873, 2016). "The binding of IL-6 to its receptor gp130 activates JAK2 which goes on to activate several downstream tumor promoters such as STAT3." (PMID 27756885, 2016). "In support of the important role of IL-6 in promoting cancer growth in the bone marrow, blockade of IL-6 by neutralizing antibody as well as inhibition of JAK2 by small-molecule inhibitors significantly blocked tumor growth." (PMID 27049717, 2016). "These cases were further tested by FISH and three of them (75%) exhibited co-amplification of PD-L1/JAK2/PD-L2 genes; two cases exhibited low amplification (~4 copies of PD-L1 gene) while the third case harbored ≥6 copies of PD-L1 per tumor cell." (PMID 27861596, 2016). "Provided the relatively low incidence of the single gene mutations, clonal mutations (detected in >20% of tumor population) were grouped into the JAK/STAT (IL7R, JAK2, JAK1, CRLF2 mutations and CRLF2-rearrangements) and RAS/RTK (FLT3, KRAS, NRAS) pathways." (PMID 26883104, 2016). "PLA2R1 is downregulated in malignant PTC versus benign disease, and appears to suppress tumorigenesis by activating the tyrosine kinase JAK2." (PMID 27633254, 2016). "Fat accumulation in the bone marrow provides a niche for tumor cells promoting their proliferation by IL-6 and JAK2." (PMID 27049717, 2016). "Activation or overexpression of JAK2, Src and Akt pathways contributes to tumor growth, angiogenesis, metastasis, and/or invasion of human NSCLC cells." (PMID 27385117, 2016). "Inhibition of IFN-α-stimulated STAT3 activation by emodin is consistent with previous observations that emodin inhibits Jak2 to suppress activation of STAT3 in tumor cells." (PMID 26683360, 2016). "Similar to the orthotopic location, we now find that SSM2 tumor cells growing in bones of OVX mice show phosphorylation of JAK2 and STAT3, suggesting activation of the PrlR signaling pathway in the absence of estrogen." (PMID 27391074, 2016). "The intragastric administration of MSM and subcutaneous implantation of tamoxifen tablets led to tumor growth suppression and inhibition of the Janus kinase 2 (Jak2)/signal transducer and activator of transcription 5b (STAT5b) pathway." (PMID 26084564, 2015). "Recently, in a comprehensive analysis of tumor grafts derived from head and neck tumor patients, dasatanib displayed in vivo efficacy when combined with the JAK2 inhibitor BMS911543 in tumor-bearing mice." (PMID 25779657, 2015). "In this study, we investigated the effect of TG101348 (a JAK2 inhibitor) on the tumor growth of erlotinib-resistant NSCLC cells." (PMID 25869210, 2015).
tumor (continued). "In contrast, JAK2 inhibitor, ruxolitinib, significantly suppressed tumor cells viability in the K-Ras mutant cancer cells, which indicates that JAK2-STAT3 signaling contributes to the drug resistance in this model." (PMID 25961376, 2015). "Pre-clinical studies have implicated JAK2 signaling as a mechanism of escape from targeted therapies in TNBC and as a promoter for the emergence of more invasive tumor cells." (PMID 26317899, 2015). "We further assessed the anti-tumor effects of JAK2/STAT3 inhibitor and MEK inhibitor as single agents and in various combinations in K-Ras mutated pancreatic and colon cells in vitro, as well as nude mice tumor model in vivo." (PMID 25961376, 2015). "We also evaluated the effect of ART on phosphorylation level of p38, ERK, CREB, STAT5, and JAK2 in CML tumor tissues." (PMID 25738364, 2015). "We used a pooled sample comprised of an unrelated normal breast, and individual TNBC, ER+, and HER2+ tumor tissues to generate a standard curve for assaying JAK2, PD-L1 and PD-L2 expression in our TNBC cohort." (PMID 26317899, 2015). "These novel data suggest that the inclusion of a JAK2/STAT3 inhibitor such as CYT387 with paclitaxel has the potential of reducing the tumor volume further than that achieved by using chemotherapy alone." (PMID 24782986, 2014). "Isolated ascites-derived tumor cells from four patients (Ascites 5, 6) were treated with paclitaxel and the activation of JAK2 (Tyr1007/1008) and STAT3 (Tyr-705) were analysed by immunofluorescence." (PMID 24886434, 2014). "The in vitro suppression of CSC-like characteristics and activation of JAK2/STAT3 pathway by CYT387 is mimicked in in vivo mouse xenografts with a reduced tumor burden." (PMID 24886434, 2014). "Previous reports have shown that multi kinase inhibitors such as AT9283 and CEP-701 that block Aurora A and JAK2 among other kinases inhibit tumor growth potently (see more below)." (PMID 24930769, 2014). "Tumor cells from mice which survived the paclitaxel treatment were found to have an activated JAK2/STAT3 pathway and to have significantly enhanced staining of embryonic stem cell transcription factor Oct4 and CSC-like marker CD117." (PMID 24782986, 2014). "Lastly, when T98G cells were injected into nude mice, G6 treatment significantly reduced tumor volume and this was concomitant with significantly decreased levels of phospho-Jak2 and phospho-STAT3 within the tumors themselves." (PMID 25162558, 2014). "Mostly from mouse studies, the JAK2/STAT3 signaling pathway has emerged as a “master switch” of tumor-induced immune suppression." (PMID 24324467, 2013). "In conclusion, our data indicate that resveratrol has potent anti-tumour effects against malignant NK cells that are mediated through inhibition of constitutively active STAT3 signals due to blocking JAK2 kinase." (PMID 23372833, 2013). "Phosphorylation of JAK2 or STAT5 in tumor cell lines with rHuEpo, molecules more specific to the EpoR signaling pathway, was rarely reported." (PMID 23861852, 2013). "Selective Jak1 and Jak2 inhibitors can also inhibit Il-6/Stat3 signaling and concomitantly reduce tumor growth in xenograft models." (PMID 23520493, 2013). "Mechanically, we found AKT/mTOR, ERK, as well as JAK2/STAT3 pathways account for the anti-tumor effects of simvastatin." (PMID 23690956, 2013). "MAC-1/2A/2B by simultaneously modelling CTCL and JAK2-translocation neoplasia should be useful tools for preclinical development and assessment of novel targeted therapies." (PMID 23372669, 2013). "786-O tumor cells contained constitutively activated p-JAK2, which was dose-dependently inhibited by Icaritin." (PMID 24324713, 2013). "Herein we provide evidence of the anti-tumor effect of blocking JAK2/STAT3 pathway by using the JAK2 inhibitor AZD1480 in 3 different types of pediatric solid tumor models." (PMID 23531921, 2013).
tumor (continued). "To address the importance of JAK2/STAT3 signaling in human tumor tissue samples, we performed immunohistochemistry (IHC) for JAK2, STAT3 and pSTAT3Y705 on a clinically annotated tissue microarray containing 245 stage I/II NSCLC samples." (PMID 22319590, 2012). "A number of experimental strategies targeting the Jak2/STAT3 pathway have been shown to enhance the anti-tumor effects of immune-based therapies in pre-clinical tumor models." (PMID 22899991, 2012). "HSE directly shows its ability to control various cellular processes such as cell cycle by inhibiting the expression of Cyclin D1, tumor growth and metastasis by down-regulating the Jak2/STAT pathways." (PMID 22792362, 2012). "Cucurbitacin E also suppressed tumor angiogenesis through interacting vascular-endothelial-growth-factor-receptor-2-(VEGFR2-) mediated Janus kinase 2 (Jak2)-signal transducer and activator of transcription 3 (STAT3) signals." (PMID 22272214, 2012). "IL-17 mediated tumor-promoting role involves a direct effect on HCC cells through IL-6/JAK2/STAT3 induction by activating the AKT pathway." (PMID 22171994, 2011). "Accordingly, inhibiting this signaling axis by the use of specific small molecule inhibitors of JAK2 has recently been investigated as a point of therapeutic intervention in multiple human tumor indications." (PMID 21533169, 2011). "Among the here identified tumor stellate cell specific genes, JAK2 and CELSR3 pose interesting targets for developing therapeutic strategies." (PMID 20416094, 2010). "Pretreatment of the cells was necessary in order to avoid JAK2/STAT3 inhibition in the tumor cells while focusing on signaling events within the APC." (PMID 19718269, 2009). "Perhaps it is the tumor expression of IL-23, IL-6, epidermal growth factor or Janus kinase 2 or an undefined factor that ultimately regulates the expression of PBMC p-STAT-3 levels, but this was not determined in our current study." (PMID 19900287, 2009). "JAK2-rearranged neoplasms exhibit a diverse and heterogeneous clinical presentation." (PMID 41530508, 2026). "Thus, our results suggested that MCPIP1 reduced hybrid EMT and tumor stemness in PC cells by inhibiting the IL6/JAK2/STAT3 signaling axis." (PMID 40874680, 2025). "In NSCLC, activation of the JAK2/STAT3 pathway promotes tumor progression." (PMID 39840666, 2025). "We observed that miR‐224‐5p could bind to and inhibit IL6ST expression and JAK2/STAT3 signaling pathway, and the inhibition of NSCLC tumor growth and JAK2/STAT3 pathway by miR‐224‐5p could be reversed by IL6ST overexpression." (PMID 39840666, 2025). "Key pathways such as the Wnt/β-catenin, VEGF, PI3K/AKT, and JAK2/STAT3 pathways are central to endothelial cell proliferation, migration, and vascular maturation, whereas interactions with tumor-associated macrophages (TAMs) and pericytes further remodel the TME to support neovascularization." (PMID 40438141, 2025). "The inhibition of the Jak2/Stat3 signaling pathway represents a promising therapeutic approach for NB, as it not only blocks survival signals but also interferes with mechanisms that promote tumor invasion and metastasis." (PMID 40429864, 2025). "Moreover, elevated JAK2/STAT3 pathway activation in TNBC associates with resistance to targeted therapies and promotes more invasive tumor characteristics." (PMID 40649917, 2025). "Additionally, B7-H3 induces epithelial–mesenchymal transition (EMT) in tumor cells through the JAK2/STAT3 pathway, thereby increasing their invasive and metastatic potential." (PMID 41463642, 2025). "An immunosuppressive tumor microenvironment is induced and cancer progression is deteriorated by abnormal stimulation of the Janus kinase 2/signal transducer and activator of transcription 3 (JAK2/STAT3) signaling pathway." (PMID 40149863, 2025).
tumor (continued). "Importantly, the potential anti-tumor mechanisms of STA confirm that the JAK2/STAT3 pathway in macrophages is a potential therapeutic target." (PMID 39974738, 2025). "Extensive mechanism studies have shown that curcumin can regulate various intracellular signaling pathways essential for cancer cell survival, growth, and invasion, such as NF-κB, JAK2/STAT3, and PI3K/AKT signalings, which underlies its broad tumor-suppressing effects against multiple cancer types." (PMID 40447190, 2025). "Therefore, CHZ868 has the potential to enhance CAR-T cell anti-tumor efficacy not only in JAK2-related tumors, but also in a broader range of malignancies." (PMID 39891728, 2025). "Together, these data substantiate the hypothesis that FPHPE exerts anti‐inflammatory and anti‐tumor effects through targeted inhibition of the JAK2/STAT3 signaling cascade, reinforcing its potential as a dual‐action therapeutic agent in HCC management." (PMID 41200213, 2025). "Osteopontin (OPN), a secreted extracellular matrix protein, that interacts with Integrins, functions as a Th1 cytokine, is involved in tissue remodeling and intricately linked to the JAK2/STAT3 and PI3K/Akt signaling pathways in HCC, contributing to tumor growth, invasion, and metastasis." (PMID 40269686, 2025). "As an extension of our previously established conceptual framework, in which PTPRO downregulates tyrosine phosphorylation of multiple oncogenic pathways in breast carcinogenesis, we experimentally confirmed the functional association between PTPRO phosphatase activity and the JAK2–YAP axis." (PMID 40016288, 2025). "Additionally, in vivo experiments demonstrated that Prkci knockout in colorectal cancer cells reduced tumor growth, angiogenesis, and Jak2/Stat3 activation, significantly extending survival in a mouse model." (PMID 40840329, 2025). "Interestingly, in the presence of fedratinib and CHZ868, CD19 CAR-T cells maintained their anti-tumor function even in the multiple rounds of tumor rechallenge, including JAK2 wild-type REH cells." (PMID 39891728, 2025). "Similarly, the upregulation of miR-135b-5p in gastric cancer promotes tumor invasiveness by targeting CLIP4, thereby impairing the tumor-suppressive JAK2/STAT3 signaling pathway." (PMID 41229433, 2025). "Additionally, LCN2 binds to SLC22A17 on tumor cells themselves, activating JAK2/STAT3 and upregulating VEGF-A expression, thereby promoting tumor angiogenesis." (PMID 41436606, 2025). "We use the following terms: perturbed spots are those that undergo in silico perturbation; predicted spots are those for which rGEX is predicted and evaluated; source state and target state are gene expression states before and after perturbation (e.g., tumor vs. Jak2-KO tumor)." (PMID 41292874, 2025). "Investigating the synergy between JAK2 inhibitors and immune checkpoint inhibitors may also offer a promising approach to reinvigorate anti-leukemic immune responses in the tumor microenvironment." (PMID 40486651, 2025). "However, our study demonstrated enhanced anti-tumor effects in REH cells, which lack JAK2 mutations and were unaffected by CHZ868 monotherapy when combined with CD19 CAR-T cells." (PMID 39891728, 2025). "Given the pivotal role of the IL6/JAK2/STAT3 axis in promoting tumor progression and shaping an immunosuppressive microenvironment, we performed immunohistochemical analysis of phosphorylated JAK2 and STAT3 in tumor tissues from the mouse model to validate pathway activation." (PMID 40384867, 2025). "JAK2 mRNA in directly inhibited by miRNA‐216a resulting in a reduction of tumour volume." (PMID 39855897, 2025). "CD276 promotes epithelial-mesenchymal transition (EMT) and HCC invasion through the JAK2/STAT3/slug pathway and induces M2 polarization of tumor-associated macrophages (TAMs) to promote an immunosuppressive tumor microenvironment (TME) in a STAT3-dependent manner." (PMID 39640777, 2024).
tumor (continued). "Mechanistically, RNF122 may enhance tumor progression through JAK2/STAT3/c‐Myc signaling pathway activation." (PMID 39218810, 2024). "Notably, QRHX inhibits inflammation and the CXCL12/CXCR4/JAK2/STAT3 signaling pathway, thereby modulating tumor-associated macrophages in murine models and suppressing tumor growth." (PMID 38920657, 2024). "In CCA tumor tissues, the expression of IL-6 was positively correlated with gp130, JAK2, and STAT3." (PMID 38881895, 2024). "Besides, we identified that a clinical anti‐inflammatory drug alminoprofen targeted C21orf58, displayed an attractive anti‐tumor efficacy on HCC treatment by preventing the formation of JAK2/C21orf58/STAT3 complex, resulting in suppression of STAT3 cascades." (PMID 38342622, 2024). "Finally, in vivo studies demonstrated that SAM decreased tumor size, and the immunohistochemical staining revealed the downregulation of p-JAK2 in the tumor tissues." (PMID 39339202, 2024). "Prior studies have indicated that inhibiting JAK2 could be a promising strategy to mitigate cell proliferation and induce apoptosis in tumor cells." (PMID 38706884, 2024). "Direct interactions of the protein with Janus kinase 2 (JAK2) and signal transducer and activator of transcription 3 (STAT-3) cause the phosphorylation of the latter and induce TNF-α and IL-1β secretion, which in turn facilitate tumour metastasis." (PMID 39273582, 2024). "Furthermore, TNKS1BP1 knockdown synergized with anti-PD-L1 treatment by upregulating PD-L1 expression on tumor cells via the JAK2/STAT3 pathway and augmenting the infiltration and effector function of cytotoxic T lymphocytes." (PMID 39019859, 2024). "Thus, a comprehensive study is necessary for understanding JAK2/STAT5A-mediated promotion of VM at tumor microecological level." (PMID 39310105, 2024). "Collectively, RNF122 enhances tumor development through JAK2/STAT3/c‐Myc signaling axis activation." (PMID 39218810, 2024). "It is secreted by TAMs and promotes tumor-cell proliferation via the JAK2/STAT3 signaling pathway." (PMID 39199574, 2024). "Whole-exome sequencing of their tumor tissues obtained at baseline and after disease progression revealed over 90% truncating dysfunctional mutations in both JAK1 (Q503* nonsense mutation) and JAK2 (F547 splice-site mutation)." (PMID 38785789, 2024). "Moreover, Snail was confirmed to be one of the downstream molecules of JAK2/STAT3 in promoting tumor metastasis." (PMID 38182570, 2024). "In addition, JAK2 inhibitor (NVP‐BSK805) treatment reduced the SASP expression to enhance docetaxel anti‐tumour effects." (PMID 39270064, 2024). "Moreover, genetic approaches to eliminateSTAT3 expression or administration of inhibitors of JAK2 or STAT3contribute to decreasing tumor fibrosis and pancreatic stellate cellsand altering the type of immune cells infiltrating the tumor." (PMID 38559310, 2024). "JAK2/STAT3 is a classical signaling pathway in tumor research." (PMID 38420199, 2024). "In addition, we found that the interaction network involving JHDM1D/KDM7A was associated with RAF1, ARAF, JAK2, and CAMK2 activation, reinforcing the involvement of JHDM1D/KDM7A in tumor aggressiveness and progression." (PMID 39136575, 2024). "In addition, it has been demonstrated that the over-activation of JAK2/STAT3 is implicated in AML tumorigenesis, and targeting this pathway enhances the anti-tumor effects of arsenic trioxide in AML cells." (PMID 39704857, 2024). "Additionally, research has shown that elevated ROS levels can inhibit tumor growth by suppressing JAK2/STAT3 signaling in different cancers." (PMID 38402166, 2024). "Furthermore, Dox-induced GADD45g knockdown with concurrent JAK2 inhibition led to a partial restoration of tumor burden and a shortened survival, as compared to treatment with ruxolitinib alone." (PMID 38582902, 2024).